INS (insulin)
Diseases named in the same sentence as INS in open-access papers (continued):
Sharing a sentence is not in itself a finding about the gene and the disease.
Alzheimer disease (continued). "It was previously reported that insulin signaling is compromised in the post mortem brain samples of Alzheimer’s disease patients and intranasal insulin administration, as well as some other drugs like the insulin sensitizer metformin were shown to improve the cognitive performance." (PMID 31858268, 2020). "It is also suggested that Alzheimer’s disease (AD) may represent a consequence of a distinct form of brain specific insulin resistance and impaired glucose regulation." (PMID 32466541, 2020). "The common feature of these two diseases is insulin resistance, and thus some antidiabetic drugs, such as intranasal insulin, pioglitazone, metformin, and liraglutide, are promising drugs that could be useful in the treatment of Alzheimer’s disease." (PMID 33256267, 2020). "Metabolic diseases also exhibit insulin dysfunction, and insulin resistance in brain tissues might lead to neurodegenerative brain diseases like Alzheimer’s disease." (PMID 32575897, 2020). "Recently, it has been revealed that insulin improved Alzheimer’s disease (AD)-related dementia." (PMID 33171799, 2020). "Moreover, cold exposure altered pathways related to three neurodegenerative diseases (Huntington’s disease, Parkinson’s disease, and Alzheimer’s disease) and insulin resistance." (PMID 31530289, 2019). "Additionally, intranasal insulin administration improved memory in patients with either mild cognitive impairment or early Alzheimer’s disease." (PMID 31396113, 2019). "Moreover, the involvement of insulin in brain angiogenesis is supported by literature and this mechanism is even supposed to play a role in the pathogenesis of Alzheimer’s disease." (PMID 31694345, 2019). "Interestingly, compared with control subjects, plasma insulin levels in Alzheimer’s disease patients are higher, whereas insulin levels in the cerebrospinal fluid are lower." (PMID 30795555, 2019). "Even though insulin signaling in the CNS cannot be studied in living humans, brain slices taken post-mortem from patients with Alzheimer’s disease respond to ex vivo insulin stimulation (in terms of insulin receptor signaling phosphorylation), but not at the level of age-matched controls." (PMID 31213970, 2019). "A comparative study utilizing different mouse models of Alzheimer’s disease investigating the transport rate of insulin across the BBB will help us determine what factors might control the rate of transport due to various Alzheimer’s disease pathologies." (PMID 31213970, 2019). "This study investigated the effects of vitamins D and E on an insulin-resistant model and hypothesized that this treatment would reverse the effects of Alzheimer’s disease (AD) and improves insulin signalling." (PMID 31635074, 2019). "Insulin accumulates intraneuronally together with hyperphosphorylated tau in Alzheimer’s disease." (PMID 31213970, 2019). "In parallel, some clinical trials on nasal drug delivery for brain targeting have been carried out in humans, including insulin for Alzheimer’s disease, oxytocin for autism, schizophrenia, and major depressive disorder, and davunetide for mild cognitive impairment and progressive supranuclear palsy." (PMID 29543755, 2018). "Moreover, an interesting meta-analysis compared the efficacy of glitazones (antidiabetic and insulin-sensitizing agents) for Alzheimer’s disease (AD) and mild cognitive impairment (MCI)." (PMID 29949869, 2018). "This work demonstrates that insulin has direct effects on inflammatory cells in the brain, and may play an important role in the mechanism of action of insulin-based therapies currently being considered for CNS disorders including Alzheimer’s disease and TBI." (PMID 30148836, 2018). "Both reports revealed that nanogels are potential delivery systems that be used for the management of Alzheimer disease because insulin administration to AD patients (mild or moderate) improves their cognitive performances, brain function and preserve the rate of glucose utilization of the brain." (PMID 29789506, 2018).
Alzheimer disease (continued). "Intranasal insulin administration is a promising treatment of Alzheimer’s disease and TBI." (PMID 30148836, 2018). "This study verifies that insulin has an anti-inflammatory effect on the BV2 microglial cell line, reducing NO, ROS and cytokine production and increasing phagocytic activity, which provides further support to the use of insulin in the treatment of Alzheimer’s disease and neurotrauma." (PMID 30148836, 2018). "One link between T2D and CI might involve decreased insulin signaling in brain and/or neurons in either animal or postmortem human brains as has been reported as a feature of Alzheimer’s disease (AD)." (PMID 29945658, 2018). "Furthermore, previous studies have demonstrated that insulin treatment reduces amyloid plaques in Alzheimer's disease (AD), and normalizes the production and functionality of dopamine and ameliorates motor impairments in 6-OHDA-induced rat PD models." (PMID 29515352, 2018). "Alzheimer's disease is characterized by inadequate production of acetylcholine in the brain and recently it is referred as type 3 diabetes as insulin plays a significant role in the expression of choline acetyltransferase, the enzyme responsible for the synthesis of acetylcholine." (PMID 28951761, 2017). "Currently Alzheimer's disease is even referred to as type 3 diabetes as it can be explained through AGEs and oxidation and insulin and the cholinergic hypothesis." (PMID 28951761, 2017). "Regarding its neuroprotective roles including insulin sensitizing, anti-inflammatory and anti-oxidative effects, adiponectin may pave the road to prevent and treat Alzheimer’s disease." (PMID 28282917, 2017). "Also the diabetogenic agent streptozotocin when injected at the intracerebro-ventricular level in rats can produce an Alzheimer disease (AD) model that triggers an insulin resistant brain state." (PMID 29211033, 2017). "And the rest clusters on comprised pathways related to Toll-like receptor, Alzheimer’s diseases, Dentatorubro pallidoluysian atrophy, Cytokine–cytokine receptor interaction, Amyotrophic lateral sclerosis, Insulin, JAK-STAT and Focal adhesion signaling pathways." (PMID 28197101, 2017). "The results obtained in basic researches have suggested that systemic IR may induce brain IR, or a deficiency of insulin effects in the brain, which in turn may lead to the phosphorylation of tau and the production of amyloid beta, and to Alzheimer disease (AD)-related pathology." (PMID 28386227, 2017). "Additionally, intranasal insulin administration improves memory function, augments synaptic proteins, and significantly reduces microglia-mediated inflammation in the hippocampus in Alzheimer’s disease or traumatic brain injury in animals." (PMID 29238302, 2017). "Together, these data support the notion that changes in insulin signalling during Alzheimer’s disease may represent an insulin-resistant state in the brain, and that targeting these changes may improve outcomes for Alzheimer’s patients." (PMID 27514532, 2016). "Thus, we propose that GCS inhibition and subsequent ganglioside reduction constitute promising cellular targets for increasing insulin sensitivity in Alzheimer’s disease." (PMID 27639375, 2016). "However, by contrast, both IRS-1 and IRS-2 expressions decrease in neurons of humans with Alzheimer’s disease and both insulin and IGF-1 signaling are patently disturbed in brains affected by Alzheimer’s disease." (PMID 25755673, 2015). "The present results suggest that ghrelin might improve cognition in Alzheimer’s disease via a central nervous system mechanism involving insulin signaling." (PMID 26090621, 2015). "Altered insulin signaling in normal aging and Alzheimer's diseases." (PMID 26136647, 2015). "In this regard, it has even been proposed that Alzheimer's disease may be considered a form of type 3 diabetes, based on the evidence for insulin resistance and impaired insulin-response pathways in the Alzheimer's-affected brain." (PMID 25977822, 2015).
Alzheimer disease (continued). "Aberrant protein aggregation is a common feature of late-onset neurodegenerative diseases such as Alzheimer’s disease and inhibition of the insulin/IGF signaling pathway has been shown to reduce the toxic aggregate prone proteins in a worm model of Alzheimer’s disease." (PMID 24474199, 2014). "In addition, over-activated insulin and PI3K/Akt pathways were associated with many pathology characteristics of Alzheimer’s disease (AD)." (PMID 25247581, 2014). "Regarding the GHRH-GH-IGF axis, MIA-690 decreased the secretion of IGF-I in the supernatant of HCN-2 cell cultures which is critical since in Alzheimer's disease one of the most important pathologic phenomena, is the competition of insulin and amyloid-β for insulin-degrading enzyme (IDE)." (PMID 23211425, 2012). "IDE is another potential explanatory link between insulin and Alzheimer's disease." (PMID 22389813, 2011). "Impaired insulin signalling is increasingly thought to contribute to Alzheimer's disease (AD)." (PMID 21347323, 2011). "Interestingly, both GSK-3β and TRPM2 channels have been implicated in a number of overlapping pathophysiological processes ranging from pancreatic insulin secretion to Alzheimer's disease." (PMID 22188973, 2011). "In this chapter we will review the relationships between some disorders of metabolism related to insulin dysfunction and cognitive decline and the importance of these alterations to the neurodegenerative process in aging-related disorders, particularly Alzheimer's disease." (PMID 22389813, 2011). "Therefore, in states of possible chronic brain high insulin concentrations, A-beta can accumulate, oligomerize, and form plaques, leading to a neurotoxicity and Alzheimer's disease." (PMID 22389813, 2011). "For instance, the insulin-degrading enzyme and neprilysin are two metalloproteases that contribute to amyloid β-peptide degradation, which therefore represents attractive therapeutic targets for Alzheimer’s disease." (PMID 21998752, 2011). "Reduction of insulin/IGF-1 signaling (IIS), a prominent lifespan, developmental and reproductive regulatory pathway, protects worms from proteotoxicity associated with the aggregation of the Alzheimer’s disease-linked Aβ peptide." (PMID 20003171, 2010). "There is increasing evidence that insulin also plays a role in Alzheimer's disease (AD) as it is involved in the metabolism of β-amyloid (Aβ) and tau, two proteins that form Aβ plaques and neurofibrillary tangles (NFTs), respectively, the hallmark lesions in AD." (PMID 19936237, 2009). "Accumulated evidence suggests that insulin resistance and impairments in cerebral insulin receptor signaling may contribute to age-related cognitive deficits and Alzheimer's disease." (PMID 18215309, 2008). "The ability of ketone bodies to affect insulin sensitivity, as well as act as an alternate energy source to glucose, may help ameliorate the increased cerebral amyloid burden that correlates with the high-glycemic state seen in Alzheimer's disease." (PMID 41473190, 2025). "Furthermore, neuronal insulin signaling and insulin resistance may impact downstream signaling and synaptic plasticity, known to be impaired in neurodegenerative diseases such as Alzheimer’s disease." (PMID 39456952, 2024). "Indeed, similar to the therapeutic repurposing of glucagon-like peptide-1 (GLP-1) mimetics and analogs, irisin’s ability to enhance insulin signaling suggests it could be a promising candidate for Alzheimer’s disease (AD) therapy." (PMID 39769243, 2024). "Furthermore, there were negative associations between fasting insulin and the outcomes all-cause dementia and Alzheimer’s disease, although the associations did not remain after Bonferroni correction." (PMID 37091584, 2023). "Moreover, it is not reported whether and how glycogen synthase kinase‐3β (GSK‐3β), a crucial kinase in insulin resistance and Alzheimer disease‐like pathologies, play a role in linking ApoE ε4 and cognitive impairment." (PMID 37700547, 2023).
Alzheimer disease (continued). "The role of CNS insulin on cognition has been further understood through several studies that suggest attenuated insulin action in the brain may be a critical factor in the development of age-related cognitive decline and Alzheimer’s disease (AD)." (PMID 37379265, 2023). "Therefore, combining either one or two of those three drugs, and administering them with intranasal insulin plus edaravone, might offer the best chance to cure many patients with Alzheimer’s dementia." (PMID 37176592, 2023). "The effectiveness of insulin for Alzheimer’s disease may be explained from the viewpoint of metabolic stress as follows: metabolic stress causes the onset of insulin resistance and lowers the removal rate of amyloid β proteins from the brain, thereby promoting their accumulation." (PMID 35558436, 2022). "Understanding the mechanism by which insulin is produced and acts in the brain may aid in the development and refinement of insulin as a therapeutic option to treat obese, diabetic, and even possibly Alzheimer's disease patients." (PMID 36244663, 2022). "Among them, the “insulin secretion” pathway contains 6 up-regulated genes and 4 down-regulated genes, the “Parkinson disease” pathway includes 2 up-regulated genes and 14 down-regulated genes, and the “Alzheimer disease” pathway embodies 7 up-regulated genes and 14 down-regulated genes." (PMID 35684108, 2022). "Interestingly, human preclinical studies have shown that Alzheimer’s disease (AD) is a degenerative metabolic disease, which is characterized by impairments in brain insulin responsiveness, glucose and energy homeostasis; it is therefore known as type 3 diabetes." (PMID 36010613, 2022). "Therefore, endothelial insulin resistance could lead to BBB dysfunction, which is associated with neurodegenerative diseases such as Alzheimer’s disease (AD)." (PMID 35974022, 2022). "Moreover, our study is unable to differentiate between different sub-types of dementia (e.g., Alzheimer’s disease), which may be more sensitive to glucose or insulin." (PMID 33868373, 2021). "In addition, lower insulin levels in the cerebrospinal fluid and a reduced expression of insulin receptors throughout the central nervous system have been found in patients with Alzheimer's Disease." (PMID 34540446, 2021). "•Brain insulin signaling may play an important role in the pathogenesis of Alzheimer's disease." (PMID 33845179, 2021). "Cerebral insulin resistance and mitochondrial dysfunction have emerged as important contributors to pathogenesis supporting our hypothesis that cerebral fructose metabolism is a key initiating pathway for Alzheimer’s disease." (PMID 33024433, 2020). "Furthermore, it has also been reported that intranasal insulin (Ins) administration improved cognitive function in patients with neurodegenerative disorders such as Alzheimer disease, and that exendin-4 (Ex-4) enhanced lifespan and ameliorated glucose homeostasis in a mouse model of HD." (PMID 32547392, 2020). "Insulin peptide signaling may also play a role in Alzheimer’s Disease (AD)." (PMID 32497060, 2020). "Also, impaired insulin signaling pathways and reduced glucose transporter levels are seen in Alzheimer’s disease and could support that a hypoglucose metabolism leads to induce cognitive decline." (PMID 31675964, 2019). "This suggests in Alzheimer’s disease in humans that insulin BBB transport might be impaired." (PMID 31213970, 2019). "On the other hand, brain insulin dysregulation plays an important role in the pathogenesis of neurodegenerative diseases such as Alzheimer Disease (AD) to the extent that AD is sometimes called type 3 diabetes." (PMID 31031891, 2019). "Therefore, the protective effects of insulin in Alzheimer’s disease could be due to pericyte protection from Aβ toxicity." (PMID 31213970, 2019).
Alzheimer disease (continued). "The adipocyte-secreted protein adiponectin (APN) has several protective functions in the peripheral tissues including insulin sensitizing, anti-inflammatory and anti-oxidative effects that may benefit neurodegenerative diseases such as Alzheimer’s disease (AD)." (PMID 28282917, 2017). "In addition, impaired insulin signaling in the Alzheimer’s disease brain may promote Aβ production, impair Aβ clearance and induce tau hyperphosphorylation, thereby leading to deterioration of the disease." (PMID 26658276, 2015). "Insulin signaling appears to play a key role in regulating lifespan and inadequate insulin action may limit glucose utilization, synaptic plasticity, and survival signaling in Alzheimer’s disease." (PMID 25965336, 2015). "While peripheral hyperinsulinaemia contribute to the development of Alzheimer’s disease, the administration of intranasal insulin, which travels directly into the central nervous system, may enhance cognition in patients with early Alzheimer’s disease or Mild Cognitive Impairment." (PMID 26193295, 2015). "Serum levels of insulin and insulin-like growth factors and their binding proteins (IGFs and IGFBPs, respectively) are changed in human neurodegenerative diseases of very different etiologies, such as Alzheimer’s disease, amyotrophic lateral sclerosis, or cerebellar ataxia." (PMID 26331034, 2014). "The negative effects of the HF/HFr diet on insulin sensitivity were associated with negative effects on mRNA coding for proteins associated with Alzheimer’s disease and memory loss including phosphatase and tensin homolog (Pten), Tau and amyloid precursor protein (App)." (PMID 24349472, 2013). "Conversely, with the increase on insulin resistance and its decreased brain actions, occurs as an accumulation of A-beta inside the cell, which could be one of the first mechanisms triggering neurodegeneration in Alzheimer's disease." (PMID 22389813, 2011). "The results of the present study suggest that dicholine salt of succinic acid, a novel neuronal insulin sensitizer, ameliorates cognitive deficits and neuronal dysfunctions in animal models relevant to age-related cognitive impairments, vascular dementia, and Alzheimer's disease." (PMID 18215309, 2008). "The results of the present study suggest that dicholine salt of succinic acid, the novel neuronal insulin sensitizer, ameliorates cognitive deficits and neuronal dysfunctions in animal models relevant to age-related cognitive impairments, vascular dementia, and Alzheimer's disease." (PMID 18215309, 2008). "Antidiabetic drugs could be potentially useful in treating Alzheimer's disease: PPAR gamma agonists, by improving insulin sensitivity, decreasing inflammation and improving cerebral energy metabolism; intranasal insulin, by restoring brain insulin levels in Alzheimer's disease." (PMID 17096857, 2006). "Interestingly, Intranasal insulin, metformin, incretins, and thiazolidinediones are a few examples of anti-diabetic drugs that have been demonstrated in human studies to improve cognition and memory in individuals with mild cognitive impairment and Alzheimer’s disease." (PMID 40257540, 2025). "Reductions in brain insulin sensitivity and cerebral blood flow (CBF) have emerged as potential factors contributing to Alzheimer's disease and related dementia." (PMID 41439617, 2025). "The genes were enriched in pathways related to insulin signaling pathway, Wnt signaling pathway, AGE-RAGE signaling pathway in diabetic complications, Alzheimer disease, Huntington disease, as determined by Kyoto Encyclopedia of Genes and Genomes (KEGG)." (PMID 39238039, 2024). "Hence, the developed insulin chitosan-coated transfersomes proved to lead to increased brain drug delivery through the intranasal route, with decreased systemic distribution and good neuroregeneration capability, making them a promising alternative for future Alzheimer’s disease treatments." (PMID 37895895, 2023).